MRPL10 (mitochondrial ribosomal protein L10)
Synonyms: L10mt; MRP-L10; MRP-L8; MRPL8; RPML8; MGC17973; uL10m
Tractability: Small molecule: a structure with a bound ligand is known. PROTAC: ubiquitination databases record sites on it; its protein half-life has been measured.
Gene: Protein-coding gene on chromosome 17 (47,823,272 to 47,831,541, reverse strand). Ensembl gene ENSG00000159111.
Subcellular location: Mitochondrion
Subcellular location (Human Protein Atlas): Mitochondria
Pathways (Reactome):
Metabolism of proteins: Mitochondrial ribosome-associated quality control; Mitochondrial translation elongation; Mitochondrial translation initiation; Mitochondrial translation termination
Gene Ontology:
Molecular function: protein binding; RNA binding; structural constituent of ribosome
Biological process: mitochondrial translation; translation
Cellular component: mitochondrial large ribosomal subunit; mitochondrion; mitochondrial inner membrane; ribonucleoprotein complex
Genetic constraint (gnomAD): Loss-of-function variants: 14 observed, 19.66 expected, observed/expected ratio (o/e) 0.71, 90% interval 0.47 to 1.11. The upper end of that interval is the gene's LOEUF score, 1.11, which puts it in group 4 of 6, group 1 being the genes least tolerant of losing a copy. Missense variants: 318 observed, 326.78 expected, observed/expected ratio (o/e) 0.97, 90% interval 0.89 to 1.07. Synonymous variants: 129 observed, 133.38 expected, observed/expected ratio (o/e) 0.97, 90% interval 0.84 to 1.12.
Homologues: Orthologues: chimpanzee MRPL10 (95% identical), dog MRPL10 (86% identical), rabbit MRPL10 (82% identical), pig MRPL10 (82% identical), mouse Mrpl10 (78% identical), rat Mrpl10 (77% identical), guinea pig MRPL10 (74% identical), zebrafish mrpl10 (46% identical), tropical clawed frog mrpl10 (42% identical).
Diseases named in the same sentence as MRPL10 in open-access papers:
MRPL10 is named in the same sentence as 11 diseases in open-access papers, as found by Europe PMC text mining. Sharing a sentence is not in itself a finding about the gene and the disease. The quoted sentences say what the papers report.
ovarian carcinoma (3 papers, 2021 to 2025). A malignant neoplasm originating from the surface ovarian epithelium. "MRPL10 has been linked to lower tumour recurrence in ovarian cancer, however it has also been associated with aggressive molecular subtypes in LUAD and LUSC." (PMID 39354291, 2024). "For example, in ovarian cancer, increased MRPL10 expression may have a protective response, whereas in lung cancer, high expression is associated with poorer outcomes and drug resistance." (PMID 39354291, 2024). "This suggests that increased expression of MRPL10 may be a protective response to upregulation of HE4 in ovarian cancer." (PMID 39354291, 2024). "In ovarian cancer, through gene expression analysis of tumours, significant upregulation of MRPL10 in response to HE4 overexpression has been observed, although MRPL10 overexpression was also correlated with progression free survival." (PMID 39354291, 2024). "Six MRPs (MRPL10, MRPL15, MRPL36, MRPL39, MRPS16, and MRPS31) related to HE4 in ovarian cancer were selected." (PMID 33934540, 2021). "MRPL10, MRPL15, MRPL36, MRPL39, and MRPS16 were highly expressed in ovarian cancer, whereas MRPS31 showed the opposite tendency." (PMID 33934540, 2021).
age-related macular degeneration (1 paper, 2020). Age-related loss of vision in the central portion of the retina (macula), secondary to retinal degeneration. "A single nucleotide polymorphism rs3209 in MRPL10 associated with early age-related macular degeneration (AMD) was also reported in Chinese Americans." (PMID 33238645, 2020).
cognitive decline (1 paper, 2017). "Their study found a strong association between a SNP in MRPL10 (rs62076130) and rate of cognitive decline in Alzheimer's cases (44% females; p-value = 7.8 × 10−7)." (PMID 28983317, 2017).
epilepsy (1 paper, 2023). A brain disorder characterized by episodes of abnormally increased neuronal discharge resulting in transient episodes of sensory or motor neurological dysfunction, or psychic dysfunction. "Interestingly, GWAS analysis in humans showed association of the MRPL10 gene with cytokines, which are also associated with epilepsy." (PMID 36980356, 2023).
measles (1 paper, 2023). A highly contagious viral infection caused by the measles virus. "In measles, including six in whole blood (SOAT1, COLGALT2, AC021860.1, HCG11, METTL21B, and MRPL10), six in the lung tissue (GSTM4, PAQR6, RP11-617D20.1, SNX8, METTL21B, and ANKRD27), and two in the transformed fibroblast cells (CBWD2, and TSFM)." (PMID 37020999, 2023).
cancer (1 paper, 2024). A tumor composed of atypical neoplastic, often pleomorphic cells that invade other tissues. "Therefore, further investigation into the pathways effected by MRPL10 expression would assist in clarifying the protein’s role in cancer progression across the cancer spectrum." (PMID 39354291, 2024).
MRPL10 also shares sentences with these, for which no sentence is quoted: Cognitive impairment (1 paper); infection (1); melanoma (1); peripheral nerve injury (1); tumours (1).